TLR4 (toll like receptor 4)
Diseases named in the same sentence as TLR4 in open-access papers (continued):
Sharing a sentence is not in itself a finding about the gene and the disease.
cancer (continued). "It has been proved that TLR4 agonist from Mycobacterium tuberculosis, among other known TLR agonists, can be used as a strong adjuvant to multi-epitope cancer vaccines." (PMID 35090304, 2022). "For example, TIRAP, which is involved in the Toll-like receptor (TLR4) signalling immune system pathway, was significantly correlated with CNV in 29 types of cancers." (PMID 35246158, 2022). "Our results suggested that in most types of cancer, SERCA3 expression was distinctly related to immune checkpoints, such as TLR4, ICOS, CTLA-4, PDCD1, and CD27." (PMID 36385955, 2022). "TLR4 has also been demonstrated to promote the epithelial–mesenchymal transition (EMT) and cancer cell migration." (PMID 36231099, 2022). "miR-18a-3p and miR-4286 activated the NF-κB transcription factor to increase cancer cell proliferation and motility and both inhibited expression of BZRAP1, but TAK-242 (TLR4 inhibitor) blocked this effect." (PMID 36314013, 2022). "Elevation of TLR4 expression in LPS-treated PLC5 cells promotes the formation of spheroid cells, indicating an increase in cancer precursor cells." (PMID 35955552, 2022). "It is well known that TLR4 and HIF-1α contribute to the progression of numerous inflammatory diseases, including cancer." (PMID 35464826, 2022). "In this study, OTUD6B expression has been unraveled to be positively correlated with most of the 47 immune checkpoint genes in almost all cancers, such as CD276, VEGFA, HMGB1, and TLR4." (PMID 36052059, 2022). "TLR1, TLR2, TLR3, TLR4, and TLR5 expression levels were high across the six immune subtypes in the pan-cancer data; TLR6, TLR7, TLR8, and TLR10 expression levels were moderate; and TLR9, TLR12P, and TLR8-AS1 expression levels were extremely low." (PMID 35801728, 2022). "In cancer or certain chronic inflammatory diseases, it acts as a DAMP molecule; binds with TLR4, RAGE, and calcium ions; and regulates biological processes, such as cell proliferation and cell migration." (PMID 35741040, 2022). "Administration of DOX increases HMGB1 expression and induces TNF- secretion via TLR4, whereas HMGB1 released from necrotic cancer cells treated with necrosis inducers increases regrowth and metastasis of residual cancer cells through RAGE activation." (PMID 35340325, 2022). "It has been shown that a synthetic TLR-4 agonist, Glucopyranosyl Lipid A (GLA)-SE, provides a promising effect on cancer progression in the perioperative context in animal models." (PMID 35185893, 2022). "Many previous studies have demonstrated the regulation of TLR-4, AKT and ERK1/2 expression in cancer cell lines in response to herbal extracts treatments (16, 17 and 20)." (PMID 34904014, 2021). "The compounds contained in propolis inhibit multiple signaling pathways crucial for cancer initiation, progression, and metastasis, such as PI3k/AKT/mTOR, NFκB, JAK-STAT, TLR4, VEGF, TGFβ, and intrinsic and extrinsic apoptosis pathways." (PMID 34444754, 2021). "Treatment with TLR-4 agonist, E6020, increased efficacy of trastuzumab and protected mice after re-challenge with HER2-positive cancer cells." (PMID 33919517, 2021). "Upon cancer cell death, HMGB1 is released in the surrounding TME where it physically interacts with several pattern recognition receptors (PRRs), such as TLR2, TLR4, and RAGE, thus stimulating the innate immune system." (PMID 33540645, 2021). "CRT exposed on the surface of dying cancer cells promotes the engulfment of dying cancer cells by antigen-presenting cells (APCs), whereas HSPs and HMGB1 bind to TLR4, enhancing APC activation and antigen cross-presentation." (PMID 34683961, 2021). "TLR2, TLR4, TLR9, and RAGE have been identified as the most common receptors for HMGB1 on cell surface in different cancer models and patients." (PMID 33614649, 2021). "TLR4 is one of the cell surface receptors of HMGB1, and TLR4/NF-κB pathway is reported to be responsible for cancer metastasis." (PMID 34552063, 2021).
cancer (continued). "For instance, CCL2 mediates lung overexpression of endogenous toll-like receptor 4 (TLR4) ligands such as S100A8, which can enhance cancer cell survival in target organ." (PMID 34249913, 2021). "Upon release from dying cancer cells, HMGB1 serves as a cognate activating ligand for Toll-like receptor 4 (TLR4) on cells of the innate immune system such as dendritic cells." (PMID 34869014, 2021). "In cancer immunotherapy, gut microbiota enhanced cancer response to the combination of CpG and anti-IL-10R through increasing tumor necrosis factor (TNF) production, which depends on the activation of TLR4 on tumor amyloid cells." (PMID 34589427, 2021). "We further found that PcrV-mediated TAM reprogramming potentiated their NO-mediated cytotoxicity against cancer cells, effects that were exerted through the activation of a PI3K/AKT/mTOR-glycolysis-NO feedback loop via direct interaction with TLR4." (PMID 34900687, 2021). "Recognition that some opioids weakly activate TLR4, but significantly prevent TLR4 activation induced by agonists, needs to be added to the list of factors that may contribute to the complexity and existing discrepancy in the field of opioid influence on cancer." (PMID 34771442, 2021). "The roles of immune and carcinoma cell surface TLR2 and TLR4 in inflammation and immunosuppression are discussed first, followed by non-inflammatory cell-intrinsic carcinoma cell TLR functions." (PMID 35048056, 2021). "Importantly, p62-deficient cancer cells, such as p62-knockdown (p62KD) SK-HEP-1, p62KD MDA-MB-231, and p62-knockout (p62KO) A549 cells, showed increased activation of autophagy induced by TLR4 stimulation, suggesting that p62 negatively regulates autophagy activation." (PMID 32384667, 2020). "Levels of LC3-II revealed increased autophagy induction in the presence of TLR4 stimulation by p62KD THP-1 and p62KD cancer cells." (PMID 32384667, 2020). "Toll-like receptor 4 (TLR4) and TLR9 agonists have been shown to decrease cancer metastasis by increasing NK cell cytotoxicity during the perioperative period." (PMID 33353113, 2020). "Although TLRs are involved in the immune response, TLR2, TLR4, and TLR9 contribute to cancer proliferation and progression." (PMID 32380783, 2020). "Having shown that p62 negatively regulates Toll-like receptor 4 (TLR4)-mediated signaling via TRAF6-ECSIT signaling axis, we herein investigated whether p62 is functionally implicated in the TRAF6-BECN1 signaling axis, thereby regulating cancer cell migration and invasion." (PMID 32384667, 2020). "Toll-like receptor 4 (TLR4)-mediated inflammatory signaling, known to recognize LPS, was described as a key player in the relationship with the malignant behavior of cancer cells." (PMID 32492880, 2020). "The investigation of molecular pathways shows that NOB is able to inhibit TLR9/IRF7 and TLR4/TRIF/IRF3 in suppressing the proliferation and growth of cancer cells." (PMID 32380783, 2020). "Suppression of TLR4 transcription by siRNAs affected myofibroblasts activity, collagen synthesis, and EMT in the human cancer cell line." (PMID 33199767, 2020). "A recent study reported that microbial stimulation of cancer cells overexpressed cathepsin K, which promoted immunosuppressive M2 TAM polarization through the TLR4-mTOR pathway." (PMID 32226493, 2020). "HMGB1, together with the surface heat shock protein 90 (HSP90), acts as a ligand of Toll-like receptor-4 (TLR4): this interaction stimulates the antigens processing by DCs, which is the premise to expand CTLs directed against cancer cells." (PMID 32331368, 2020). "Since p62 negatively regulates TLR4-mediated signals through the inhibition of TRAF6-ECSIT signaling, we therefore investigated whether p62 is functionally implicated in the TRAF6-BECN1 signaling axis, thereby regulating autophagy activation, and cancer cell migration and invasion induced by TLR4." (PMID 32384667, 2020).
cancer (continued). "Moreover, this study suggests that hemorrhage and extravascular hemolysis could provide competitive Hb and Bv signaling to nearby cells expressing TLR4, and that this process could modulate NF-κB signaling in TLR4-positive cancer cells and cancer-infiltrating leukocytes." (PMID 31163699, 2019). "However, none of the TLR4 SNPs shown significant association with early or late stages of cancer." (PMID 31278284, 2019). "Among these, ‘proteoglycans in cancer’ (P = 0.0040) and ‘NF-kappa B signaling pathway’ (P = 0.0316), involving TLR2, TLR4 and IL-12B genes, were our main focus due to their roles in immunity response." (PMID 31337442, 2019). "Evidences from recent studies suggest that enhanced expression and activity of toll-like receptor 4 (TLR4) in chronic infectious and inflammatory conditions are correlated with cancer progression." (PMID 31186484, 2019). "It has been shown that S100A9 overexpression is correlated to invasion and metastasis in various cancers, and S100A9 directly enhances tumor cell malignancy by activating TLR4-mediated or RAGE-mediated signaling cascades." (PMID 31620141, 2019). "Apart from TLR4, other TLRs as TLR2, TLR3, and TLR9 were already shown, in preceding cancer, hepatic cirrhosis." (PMID 30976817, 2019). "The evidence in our analysis demonstrated that increased expression of TLR4 predicted poor OS and DFS in patients with cancers." (PMID 29560134, 2018). "The possibility that TLR-4 may activate Wnt signaling was recently evaluated, suggesting that TLRs mediate many of these functions in immune cell types and are currently possible primary candidate molecules to be used as important adjuvants in a variety of cancers." (PMID 30680070, 2018). "To determine which HMGB1 receptor(s) is involved in mediating cell invasion, we silenced four well-recognized HMGB1 receptors (RAGE, TLR2, TLR4, and CD24) individually by transiently transfecting specific shRNA oligos in Panc-1 cancer cells for 48 h." (PMID 29615080, 2018). "Thus, TLR4 may be a critical therapeutic target for cancer cachexia." (PMID 30575787, 2018). "TLR4-transient knockdown cells had a reduction of intrinsic expressions of IL-6, IL-8 and XIAP in both cancer cells." (PMID 29486738, 2018). "However, it is very likely that the lymphangiogenic changes in cytokine and chemokine signaling caused by docetaxel is dependent on TLR4 pathway activation and without it, the cancer cell does not produce the necessary LEC-activating signals required to promote their invasion." (PMID 29976154, 2018). "TLR4 expression levels increased in BCA tissues compared to normal breast tissues and activation of TLR4 by lipopolysaccharide (LPS) mediated the cancer cell migration in vitro." (PMID 29486738, 2018). "Activation of the TLR4 pathway by LPS in BCA cells promoted cell migration and probably involved cancer metastasis." (PMID 29486738, 2018). "Therefore, target of TLR4/NF-κB signaling pathway may provide a new strategy for the treatment of human common diseases such as inflammatory disease, neurodegenerative disease, and cancer." (PMID 29441018, 2018). "This study sought to develop a simple nanoparticle-based approach to enhance the efficiency and tolerability of lipopolysaccharide (LPS), a potent ligand of Toll-like Receptor 4 (TLR4), for immunotherapy in cancer." (PMID 29902933, 2018). "Emodin, which has been isolated from rhizomes of Rheum palmatum, inhibits several target molecules in inflammation and cancer, such as NF-κB and the serine/threonine kinase Akt, both important molecules in TLR2 and TLR4 signaling pathways." (PMID 30307962, 2018). "Interestingly, PTX treatment could significantly upregulate TLR4 expression in both cancer cell lines whereas there were no significant alterations of TLR4 levels in TLR4-deficient cancer cell lines after PTX treatment." (PMID 29486738, 2018).
cancer (continued). "In summary, this meta-analysis illustrated polymorphisms of TLR4 rs4986791 and rs11536889 might make contributions to slow the formation and development of cancer, whereas rs4986790 was not strongly associated with cancer risk." (PMID 29246004, 2017). "Among these ligands, TLR2/4 agonist Bacillus Calmette-Guérin (BCG), TLR4 agonist monophosphoryl lipid A (MPL), and TLR7 agonist imiquimod have been approved for use in cancer therapy." (PMID 28216575, 2017). "We used TLR4 specific agonist and inhibitor, and shRNA-mediated knockdown of OPN to explore the effect and mechanism of TLR4 signaling on OPN expression and the metastatic phenotype of cancer cells." (PMID 29228698, 2017). "Thus, cancer cachexia may become manageable by using a single reagent that perturbs TLR4 signaling." (PMID 28536426, 2017). "While the function of FBXW7 has been most thoroughly reported in cancer, FBXW7 has also been clearly shown to downregulate TLR4 (and inflammation) in human and murine macrophages by the Sterneck group." (PMID 27812198, 2016). "Our data contribute to the understanding of the role of PLAUR in cancer and provide a rationale for addressing the correlation between PLAUR and TLR4 status, and DNA repair/CHK1 inhibitors efficiency." (PMID 27685627, 2016). "Herein, we used TLR4 agonist LPS as a tool to address how and when to use TLR agonists to effectively improve cancer immunotherapy." (PMID 26885368, 2016). "Significantly increased TLR4 expression has been observed in NSCLC and correlated with malignancy of cancer cells." (PMID 27223258, 2016). "Synthetic TLR3, TLR4, TLR7, and TLR9 ligands are being tested in cancer patients as single agent or in combination with cancer vaccines and ligands for other TLRs are in development." (PMID 28003994, 2016). "In cancer cells, exogenous HMGB1 enters the mitochondria, which is followed by the formation of giant mitochondria independently of HMGB1 receptors such as TLR4 or RAGE." (PMID 27147971, 2016). "Because microbial LPS was detected in the sera of irradiated animals, we used TLR4 agonist LPS as a tool to address how and when to use TLR agonists to potentially improve adoptive T cell transfer cancer immunotherapy." (PMID 26885368, 2016). "In BxPC-3 and MIAPaCa-2 cancer cells TLR2 and -9 expression clearly dominated (BxPC-3: TLR2 42.9%, TLR4 2.9%, and TLR9 43.8%; MIAPaCa-2 TLR2: 40.2%, TLR4 8.5%, and TLR9 88.5%) (top and center)." (PMID 27941651, 2016). "The potential use of the immunostimulatory properties of TLR agonists, particularly TLR2, TLR3, TLR4, TLR7/8, and TLR9, has been investigated in cancer immunotherapy." (PMID 25309546, 2014). "Endogenous ligands for TLR4 such as hyalouronic acid (HA) and heat shock protein 60 (HSP60) are abundantly present in malignant tumors." (PMID 25526031, 2014). "In this regard, TLR-4 SNPs of the transmembrane domain may lead to defects in intracellular receptor transfer that prevent the receptor to be converted to the cell surface where it works, and thereby may correlate with disorders in the immune system related to cancer of the intestinal mucosa." (PMID 24705379, 2014). "Whereas, the effective cancer adjuvant, BCG-CWS, activates not only TLR2, but also TLR4 and NOD2 receptors." (PMID 21533081, 2011). "To date, cancer vaccine adjuvants have included various TLR agonists such as TLR3, TLR4, TLR5, TLR7 and TLR9." (PMID 21533081, 2011). "Samples of carcinomas with recurrence exhibited a significant increase in the mRNA levels of TLR3, TLR4 and TLR9." (PMID 21129170, 2010). "The non-cancer control group was found to be in Hardy-Weinberg equilibrium at the polymorphic loci studied (chi-square H-W = 0.58 for IL8-251, 0.42 for TLR4 Asp299Gly and 0.17 for TLR4 Thr399Ile)." (PMID 17462092, 2007). "Additionally, radiation-induced HMGB1 secretion activates CAFs via TLR4/PI3K-AKT to suppress apoptosis and drive cancer radioresistance, an effect reversed by HMGB1 inhibition." (PMID 41465435, 2025).
cancer (continued). "As suggested by prior work in other cancers, a direct physical interaction between TREM1 and TLR4 may underpin the observed signaling activation." (PMID 41394801, 2025). "Notably, the co-chaperone of eHsp90, Morgana, which is secreted via unconventional pathways, enhances cancer cell motility via TLR2, TLR4, and LRP1 signaling." (PMID 41226319, 2025). "The stimulation of the TLR4 and RAGE signaling pathways by HMGB1 may promote cancer invasion and metastasis via caspase-1 activation and a cascade of inflammatory responses." (PMID 40331953, 2025). "Tlr4, Vegfa, Tgfb2 are from MMU5205 (Proteoglycans in cancer)." (PMID 39789452, 2025). "Like TLR4, there is division surrounding the role of TLR9 activation in cancer pathogenesis." (PMID 38201300, 2024). "Additionally, it activates TLR4, enhancing the expression of NLRP3 and promoting the secretion of chemotactic factors and inflammatory mediators from the cancer cells." (PMID 39610830, 2024). "ENST00000311534 was significantly correlated with HMGB1, ENST00000326094 was significantly correlated with BTN3A1, CD160, TGFBR1, and IL6R, and ENST00000375991 was significantly correlated with CD276, ENTPD1, HMGB1, TLR4, KDR, and TGFBR1 among these 33 immune genes in more than 20 cancer types." (PMID 39766805, 2024). "Additionally, TLR4-induced phosphorylation of GSK3β and ERK plays crucial roles in regulating cancer cell survival." (PMID 38930793, 2024). "ISCA1 was correlated with ENTPD1, HMGB1, TLR4, and TGFBR1 in more cancers." (PMID 39766805, 2024). "Like TLR-4, activation of TLR-2 leads to the production of pro-inflammatory cytokines that may support cancer processes." (PMID 39273213, 2024). "In comparison, two prototypical particulate β-glucans, one isolated from I. obliquus and one from Saccharomyces cerevisiae (zymosan), are agonists for Dectin-1 but not TLR2 or TLR4, and are unable to trigger anti-cancer functions of macrophages." (PMID 38396285, 2024). "Finally, 379 cancer samples from TCGA and UCSC were used to extract 76 necroptosis-related genes, including NLRP3, TLR4, and IRF6." (PMID 38750159, 2024). "TLR1 and TLR3 (Id:242667_at) exhibited reduced expression, and TLR4 (Id1552798_a_at) exhibited increased expression in individuals with cancer, independent of HPV (p < 0.05)." (PMID 39208235, 2024). "Nonetheless, the inhibition of heparanase demonstrated that heparan sulfate alone, nor TLR4 stimulation, is not sufficient to favor cancer cell stem-like properties and an active heparanase is always essential." (PMID 39349458, 2024). "Thus, we challenged Toll-like receptor 4 (Tlr4) and myeloid differentiation factor 88 (Myd88) knock-out (KO) mice with N-butyl-N-(4-hydroxylbutyl)-nitrosamine (BBN), a well-known urinary bladder carcinogen." (PMID 39000291, 2024). "The “Proteoglycans in cancer” pathway was also exclusively enriched in AA-SScL fibroblasts, driven by the upregulation of IGF2, DCN, LUM, COL1A1, COL1A2, and the receptors KDR and TLR4." (PMID 36835058, 2023). "Although many studies have focused on the relationship and effects of TLR4 and S100A8/A9 in cancer, the mechanisms that could be developed as drug targets are not well-reported, and research in this area should be constantly strengthened." (PMID 37701037, 2023). "Therefore, the RPLP2/TLR4/PI3K/AKT axis provides a signalling pathway for regulating HIF-1α and subsequently promoting aerobic glycolysis and cancer cell growth." (PMID 38052785, 2023). "In addition, many studies have shown that Toll-like receptor 4 (TLR4), NF-κB, matrix metalloprotease-2 (MMP-2), and other proteins also participate in S100A8/A9-mediated cancer cell migration and invasion through different transduction pathways." (PMID 37701037, 2023).